HGF (hepatocyte growth factor)
Diseases named in the same sentence as HGF in open-access papers (continued):
Sharing a sentence is not in itself a finding about the gene and the disease.
tumor (continued). "Hence, we injected epithelial OC cells and HGF-induced E/M hybrid state cells (HGFR182) i.p. in balb/c nude mice and monitored the tumor formation." (PMID 36765641, 2023). "In vitro, it inhibited tumor cell proliferation, survival and migration/invasion in cell lines where c-MET is activated by different mechanisms, including c-MET gene amplification, HGF/c-MET autocrine loop formation and c-MET overexpression." (PMID 36839989, 2023). "As the cancer progression, tumor cells, vascular endothelial cells, immune cells and pericytes produce excessive proangiogenic factors, such as VEGF, bFGF, and HGF, to break this balance and lead to excessive activation and recruitment of endothelial cells and pericytes." (PMID 37550755, 2023). "In addition, HGF, as an important mediator of tumor lymphangiogenesis, can bind to SRPX2 to promote tumor lymphangiogenesis." (PMID 37803421, 2023). "MET is activated by auto-phosphorylation when bound by HGF engaging several downstream signaling networks, including the PI3K/AKT/mTOR, phospholipase C (PLC), and RAS/MAPK/RAF/ERK pathways involved in tumor growth and invasion." (PMID 36831657, 2023). "Our results suggest that tumours bearing METex14 mutation, on its own with no other genetic alteration, will likely display response to MET‐targeted therapies if HGF is both present and accessible to the cancer cells." (PMID 36799689, 2023). "For example, compared with normal tissue fibroblasts, CAFs can increase tumor cell proliferation, ECM production, and also promote the secretion of various cytokines (such as stromal cell-derived factor-1 SDF-1; Vascular endothelial growth factor VEGF; HGF." (PMID 37666813, 2023). "Also, once delivered to cells, HPSE can enhance expression of molecules that drive aggressive tumor behavior including vascular endothelial growth factor (VEGF) and hepatocyte growth factor, the latter being a stimulator of cell spreading." (PMID 37091070, 2023). "Undoubtedly, targeting both HGF/c-MET and Hh pathways may produce a more desirable effect, considering the interplay between these two pathways in tumor cells and CAFs, as well as the cross-talk and autocrine mechanisms within cells." (PMID 37919751, 2023). "This may be a complex result of gemcitabine’s cytotoxicity, and the anti-CTHRC1 antibody’s inhibition of tumor ECM production and facilitation of gemcitabine sensitivity through the inhibition of growth factors, such as HGF." (PMID 37444482, 2023). "Additionally, CAFs isolated from human CRC tumors can secrete hepatocyte growth factor (HGF), osteopontin (OPN) and SDF-1 to increase CD44v6 expression in colorectal CSCs, thereby initiating tumor migration and metastasis." (PMID 37124519, 2023). "Simvastatin can also inhibit CRC liver metastasis by reducing cholesterol biosynthesis because hepatocyte growth factor (HGF) released from the liver induces SREBP2 and activates the c-Met/PI3K/AKT/mTOR axis in tumor cells to increase the cholesterol biosynthesis." (PMID 38023258, 2023). "Basophils are a source of hepatocyte growth factor (HGF), a powerful angiogenic factor in tumours." (PMID 38137361, 2023). "At our institute, immunohistochemical staining showed negative expression of HGF in tumor tissue of SCLC at our institute (47/47, 100%)." (PMID 37828456, 2023). "Our results revealed that plasma HGF rather than tumor HGF exhibited a potential role in predicting metastasis and survival in SCLC." (PMID 37828456, 2023). "Shen, W., and colleagues designed a nanoemulsion combining chemotherapy and gene therapy to simultaneously deliver doxorubicin and small interfering RNAs targeting hepatocyte growth factor (HGF) to reduce ECM deposition, induce CAF apoptosis, and reduce tumor metastasis." (PMID 37784082, 2023). "First, CAFs can facilitate tumor growth, angiogenesis, invasion, and metastasis by CAF-derived soluble molecules, and recruit suppressive immune cells by TGF-β and hepatocyte growth factor (HGF)." (PMID 37280069, 2023).
tumor (continued). "On the one hand, neutrophil promotes angiogenesis and progression of tumors through secreting tumor growth promoting factors, such as vascular endothelial growth factor (VEGF), matrix metalloproteinase, hepatocyte growth factor (HGF), interleukin 6 (IL-6) and IL-8." (PMID 37072770, 2023). "CAFs are a major component of the TME, providing physical support in it and secreting various proteins, such as extracellular matrices (ECMs), hepatocyte growth factor (HGF), insulin-like growth factor 1/2 (ILGF1/2) and cytokines that can modulate tumor growth and survival." (PMID 36835352, 2023). "Consequently, CAFs including Hp-AGFs mediate cancer-related inflammation by secreting numerous pro-inflammatory and tumor promoting factors including IL-6, IL-8, SDF-1, TGF-β, EGF, and HGF." (PMID 37460910, 2023). "Therefore, we evaluated the role of MET in a 3D system obtained by coculturing GC cell lines and patient-derived gastric CAFs and found that the HGF/MET signaling axis plays a significant role in sphere formation and tumor growth." (PMID 37887325, 2023). "Moreover, the expression of several genes involved in tumor vascularization, such as VEGF, IL-8 and hepatocyte growth factor (HGF)) was also upregulated following exposure to PMPs." (PMID 37569299, 2023). "HGF activates HGF/c-Met, ERK1/2/MAPK and PI3K/AKT pathways in tumor cells." (PMID 37842051, 2023). "Recently, we generated radiolabeled HiP‐8 (64Cu‐labeled HiP‐8‐PEG11) as a tracer for PET imaging and demonstrated in a mouse xenograft model that radiolabeled Hip‐8 accumulated selectively into the HGF‐producing tumor rather than HGF‐non‐producing tumor." (PMID 36416133, 2023). "The HGF/MET pathway has gained increasing interest in recent years for its involvement in cell growth, survival, epithelial–mesenchymal transition (EMT), metastasis, stemness, and chemoresistance in several tumor types." (PMID 37887325, 2023). "For example, NFs were induced by HPV-negative oropharyngeal cells to release hepatocyte growth factor (HGF) and IL-6, which might encourage tumor cell formation by activating c-met and STAT3." (PMID 37055382, 2023). "The MET gene is located on chromosome 7q21‐23 and encodes for a receptor tyrosine kinase, which homodimerizes upon binding to hepatocyte growth factor (HGF) and activates downstream signaling pathways such as RAS/ERK/MAPK and PI3K/AKT, thereby promoting tumorigenesis and tumor progression." (PMID 37326363, 2023). "IHC staining on the paraffin-embedded tumor specimens from 47 SCLC patients showed negative expression of HGF in each sample." (PMID 37828456, 2023). "In particular, MetMab significantly blocked HGF-dependent HCC tumor growth, but failed to inhibit growth of tumors with HGF-independent MET activation and overexpression." (PMID 37779207, 2023). "The Hepatocyte Growth Factor (HGF)/c-Met pathway is well characterized and recognized for its essential role in several cell vital processes in embryonic development, in the repair of injured tissues, as well as in carcinogenesis and tumour progression." (PMID 37835473, 2023). "CAFs, in turn, recruit endothelial and immune cells to the tumour via secreting a variety of chemokines and growth factors including VEGFA (vascular endothelial growth factor A), PDGF (platelet-derived growth factor) and HGF (hepatocyte growth factor)." (PMID 34982945, 2022). "The binding of the receptor tyrosine kinase MET, expressed on neutrophils, by the tumor necrosis factor-alpha (TNFα), and its ligand, the Hepatocyte growth factor (HGF), drives the nitric oxide synthase (NOS) and the consequent release of the anti-tumor inflammatory mediator." (PMID 35664746, 2022). "The results of this experiment showed that MACC1 could activate the HGF and then stimulate the phosphorylation of c-MET, thus enhancing the invasion ability of tumor cells." (PMID 35874635, 2022).
tumor (continued). "Various molecules originated from CAFs and tumor-infiltrating immune cells such as TGF-β, FGF, EGF, HGF, and IGF1 along with Hedgehog, Notch, and Wnt signaling pathways could promote EMT." (PMID 35769483, 2022). "Hepatocyte growth factor (HGF) acts on the HGF receptor expressed on neutrophils and promotes the production of inducible nitric oxide synthase (iNOS); iNOS releases nitric oxide and promotes apoptosis of tumor cells." (PMID 36324574, 2022). "NK4 can not only limit the growth, metastasis and invasion of tumor cells induced by HGF, but suppress tumor angiogenesis independent of the HGF/c‐Met pathway." (PMID 34981659, 2022). "HGF targeting antibodies, including rilotumumab (AMG-102), ficlatuzumab, TAK-701, and YYB-101, bind to HGF and prevent c-Met attachment, leading to the induction of synergistic anti-tumor responses combined with other TKIs and EGFR inhibitors." (PMID 35986321, 2022). "Tumor cells also recruit platelets into the tumor microenvironment (TME), and platelets are activated by tumor cells to release the cytokines VEGF, CCL5, PDGF, TGFβ, PG, TPM3, LPA, PF4, PAF, and HGF, which promote the epithelial-mesenchymal transition of tumor cells." (PMID 35836573, 2022). "This involves molecules such as FGF, HGF, amphiregulin and WNT16B recently identified as components of the SASP in the tumour microenvironment and capable of promoting tumour cell survival/disease progression and attenuating the effects of cytotoxic chemotherapy." (PMID 35177596, 2022). "In addition, IL4 induces expression of HGF, which creates an immunosuppressive environment for cytotoxic natural killer cells via c-MET signaling in tumor cells." (PMID 36077870, 2022). "Secondly, a great deal of findings reported that CAFs could accelerate tumor growth by producing epidermal growth factor (EGF), fibroblast growth factor (FGF), hepatocyte growth factor (HGF), cytokines and chemokines." (PMID 36093115, 2022). "Mechanismly, MET protein transduces extracellular matrix signals into the cytoplasm by binding to hepatocyte growth factor/HGF ligand, and regulates many physiological processes including proliferation, dissemination, morphogenesis and survival, then contributing to the tumor process." (PMID 36713541, 2022). "In addition, cMET/HGF signaling has also been shown to mediate resistance to ICI treatment, directly and indirectly, involving tumor and immune cell populations." (PMID 36761417, 2022). "Moreover, women with COPD from biomass smoke have reduced serum levels of biomarkers of angiogenesis and tumor progression (e.g., FGF-2, HGF, sVEGFR2, sHER2/neu, sTIE-2) compared to women with COPD from smoking." (PMID 35626756, 2022). "Cancer-associated fibroblasts (CAFs), the predominant stromal cells of TME, modulate tumor progression by secreting various pro-inflammatory cytokines (IL-6, IL-8, TGF-β, hepatocyte growth factor (HGF), vascular cell adhesion molecules-1 (VCAM-1), and chemokines (CXCL12, CXCL14, CXCL1)." (PMID 35927239, 2022). "Moreover, we detected the serum HGF levels in the HCC patients by ELISA and detected the ETV1 levels in the tumor tissues of HCC patients by IHC." (PMID 36109787, 2022). "Fibroblasts co-cultured with tumor cells secrete high amount of HGF as compared to fibroblasts cultured in the absence of tumor cells." (PMID 35081970, 2022). "Thus, restraining the secretion of MMP2 and CAFs activation inducers by tumour cells, cabozantinib would avoid the release by CAFs of pro–motility (SDF1) or ECM remodelling-stimulating (HGF) factors." (PMID 35106125, 2022). "Once binding to hepatocyte growth factor (HGF), it activates the downstream signaling pathways to regulate tumor progression by controlling the differentiation, proliferation, migration, and apoptosis of tumor cells." (PMID 35414783, 2022).
tumor (continued). "HGF can activate vascular endothelial cells through MAPK and PI3-K pathway, induce the proliferation and migration of vascular endothelial cells, form lumen like structure, and participate in tumor angiogenesis." (PMID 36172142, 2022). "Therefore, as a next step, we focused on the upregulation of the HGF/c-Met pathway after RFA, which was known as driving tumor growth, metastatic invasion, and aggressive tumor biology." (PMID 35710408, 2022). "They suggested that this process alters the tumour microenvironment and that several growth factors (HGF (Hepatocyte Growth Factor), FGF (Fibroblast Growth Factor) and GM-CSF (Granulocyte–macrophage-Colony Stimulating Factor)) from senescent cells can be activated to encourage tumour development." (PMID 35151278, 2022). "Tumor cells release chemoattractant proteins that recruit GAMs, such as CCL2, colony stimulating factor-1 (CSF-1), granulocyte–macrophage colony stimulating factor, hepatocyte growth factor or scatter factor, stroma-derived factor 1 (SDF-1), and GDNF." (PMID 35448036, 2022). "We showed that TAb2 tumor cells expressed higher levels of CSF1, VEGF, HGF and CXCL12." (PMID 35366939, 2022). "Consequently, the release of HGF/MET-dependent NO by neutrophils promotes cancer cell killing, abating metastasis formation, and corresponding primary tumor growth (in several cancer models)." (PMID 35664746, 2022). "Platelets contribute to tumor vascular growth through a number of platelet-derived angiogenic factors such as vascular endothelial growth factor (VEGF), platelet-derived growth factor, and hepatocyte growth factor." (PMID 35965580, 2022). "More normal and tumor saliva samples should be collected and set the positive or negative cut-off value of HGF and MMP9." (PMID 35545767, 2022). "In addition, the epidermal growth factor (EGF), hepatocyte growth factor (HGF) and platelet- derived growth factor (PDGF) produced by neutrophils can facilitate tumor progression." (PMID 35711434, 2022). "Some studies have identified several molecular mechanistic pathways that may contribute to the tumor microenvironment changes after RFA, such as IL-6, HGF/c-Met and VEGF, which were considered relevant to tumor growth, metastasis, and invasion." (PMID 35710408, 2022). "HGF stroma did not seem to impact on RANKL expression in the tumour region compared to acellular stroma." (PMID 36452176, 2022). "It was reported that HGF/c-Met could lead to initiate several downstream signaling pathways including PI3K/AKT, Ras/MAPK, JAK/STAT, which were involved in tumor progression." (PMID 35710408, 2022). "Compared to the control group, the PSC+PE and HGF+PE groups showed no significant changes in tumor volume, as well as GSH and MDA level." (PMID 35693705, 2022). "Notably, while some of the targets revealed by our analysis (such as IGF1R, HGF, and KAT6A), are well-characterized drivers of tumorigenesis, others are known tumor suppressors e.g., PTEN, EP300." (PMID 35347083, 2022). "uPA supports tumor cell proliferation by proteolytically activating various growth factors that include epidermal growth factor (EGF), fibroblast growth factor-2 (FGF-2) and hepatocyte growth factor/scatter factor (HGF-SF)." (PMID 35222418, 2022). "Furthermore, treatment of GBM xenografts with chimeric U1/ribozymes targeting HGF and c-MET mRNA sensitized tumors to gamma radiation, and greatly improved tumor regression and cure rate." (PMID 36034555, 2022). "In addition, HGF, MET amplification, and EGFR T790M lead to the upregulation of PD-L1 expression in NSCLC and promote immune escape by tumor cells through different mechanisms mediated by the PI3K-Akt, MAPK, and NF-κB pathways." (PMID 35840984, 2022). "Tumours may reprogramme MSCs to recruit them to the tumour site, where they play a tumour‐supportive role via secretion of exosomes, IL‐6, SDF‐1, PDGF and HGF in several cancers." (PMID 35908277, 2022).
tumor (continued). "Pre-clinical and clinical evidence suggests that HGF/MET inhibitors display cytostatic rather than cytotoxic activity on tumor cells." (PMID 34200749, 2021). "Classically, circulating pro-HGF is produced mainly by tissue fibroblasts, where it is biologically inactive until cleaved and activated by a variety of proteases such as hepatocyte growth factor activator (HGFA), which are also expressed by tumor cells." (PMID 34185790, 2021). "Glioblastoma xenografts in nude mice showed up to 85% less tumor growth after approximately 10 weeks of treatment with anti-HGF nanobody 1E2-Alb8, and no growth with nanobody 6E10-Alb8, as compared to untreated mice." (PMID 34769339, 2021). "In addition, c-MET oncogene, which codes for the tyrosine kinase receptor of HGF, could promote invasion and the metastatic potential of different cancers, including BC, through promoting angiogenesis, proliferation, invasiveness, and survival of the tumor cells." (PMID 34577857, 2021). "Additionally, upregulation of the HGF/c-Met signaling pathway can lead to activation of the β-catenin and PI3K/Akt pathways and deactivation of the E-cadherin pathway, promoting tumor invasion." (PMID 34513829, 2021). "Hepatocyte growth factor (HGF), also known as scatter factor, is the ligand of c-Met (mesenchymal-epithelial transition tyrosine kinase receptor or HGF receptor) that is often secreted by stromal cells and regulates the stromal-tumour interactions in PC." (PMID 34336679, 2021). "Pharmacokinetics and circulating VEGF, VEGFR2, HGF, and MET levels were evaluated in patients taking the combination of pazopanib and tivantinib; tumor pharmacodynamic responses were assessed in patients receiving only pazopanib for 7 days prior to initiating combination therapy." (PMID 34180036, 2021). "Additionally, activation of the HGF-MET pathway by overexpression and up regulation has been described as the escape resistance mechanism of tumor cells against inhibition of the EGFR, RAS-RAF-MEK, and Akt–mTOR (mammalian target of rapamycin) pathways." (PMID 33918490, 2021). "Immunohistochemistry analysis showed that p-Fis1 and HGF were expressed at higher levels in tumor tissues compared to adjacent non-tumorous tissue." (PMID 34848680, 2021). "For example, four growth factors (TGFB1, HGF, BMP1 and PDGFB) that are well-known to induce EMT, exhibited higher expression levels in CD4/8+ T cells compared with other immune and tumor cells, suggesting that anti-immune evasion promotes EMT as well by producing growth factors which induce EMT." (PMID 34158591, 2021). "Chemoattractants [inter alia, hepatocyte growth factor (HGF), TGF-β, and granulocyte-colony stimulating factor (G-CSF)] attract different cell populations to the tumor microenvironment and lead from a decreased pro-inflammatory to an amplified anti-inflammatory state." (PMID 34485282, 2021). "Compared with adjacent nontumor tissues, HGF and c-Met expression were relatively higher in tumor tissues." (PMID 34970484, 2021). "HGF secreted in a paracrine manner by tumor microenvironment-localized stroma cell and not by the tumor cells themselves has been shown to promote tumor proliferation, metastasis, and therapeutic resistance." (PMID 33718248, 2021). "TAMs secrete effector cytokines such as epidermal growth factor (EGF), platelet derived growth factor (PDGF), basic fibroblast growth factor (bFGF), hepatocyte growth factor (HGF) and TGF-β, which can promote tumor cells proliferation and survival, based on a huge number of animal studies." (PMID 34368156, 2021). "To confirm that GCMSCs-derived HGF could regulate tumor metastasis by upregulating HK2, we first investigated whether a HGF neutralizing antibody could inhibit the upregulation of HK2 expression by GCMSCs-derived HGF in HGC-27 cells in vitro." (PMID 33718248, 2021).